RAB7A (RAB7A, member RAS oncogene family)
Diseases named in the same sentence as RAB7A in open-access papers (continued):
Sharing a sentence is not in itself a finding about the gene and the disease.
tumor (continued). "Furthermore, the reduction in tumor weight observed with Rab7a KO cell injections could be partially reversed by treatment with the TPC2-A1-P agonist, with tumor weights reaching levels that were not significantly different from WT (day 14)." (PMID 39562548, 2024). "Therefore, the phosphorylation of Rab7A may play a role in the hyperproduction of cytokines in tumor progression." (PMID 34572553, 2021). "Interestingly, the tumour-associated mutant K508R displayed decreased Rab7A GAP activity and was not as effective as FLCN WT at stimulating GTP hydrolysis." (PMID 28656962, 2017). "Having established the impact of RAB5, RAB7A, and GDI2 on cellular invasion through FN-rich collagen matrices, we sought to analyze their role in early tumor dissemination events in vivo." (PMID 39630893, 2024). "Initial analyses revealed that mRNA expression of ITGB6, ERBB2, RAB5A, RAB7A, and GDI2 was all significantly higher in tumor tissue in comparison to normal tissue." (PMID 39630893, 2024). "The antagonistic relationship between RAB7A and RAB5B may represent a defensive mechanism employed by tumor cells to counteract the inhibitory effects of BmK-M9, which could disrupt vesicular transport processes critical for tumorigenesis." (PMID 40080350, 2025). "Mice injected with either TPC2 KO or Rab7a KO B16F10-luc cells exhibited significantly decreased tumor weights and reduced dissemination as well as reduced MITF and β-Catenin staining in ex vivo tumor tissue compared to mice injected with WT B16F10-luc cells." (PMID 39562548, 2024). "Cox regression analysis showed that elevated RAB7A was an independent prognostic factor, and the prognostic nomogram model included radiotherapy status, presence of postoperative tumour residual and histologic grade." (PMID 36261459, 2022). "The analysis revealed that normalization with a “hypothetical” reference gene with 0% CV across all 79 tumor and 79 normal samples (FPKM = 100, CV = 0%) maintained the separation of tumors from normal samples as did normalization with RAB7A (CV = 17%) and C1orf43 (CV = 16%)." (PMID 31409279, 2019). "Our results suggest that the tumour suppressor function of FLCN is, at least in part, due to its ability to inhibit the oncogenic signalling of EGFR, by acting as a GAP protein for Rab7A and therefore modulating the fate of receptor trafficking following endocytosis." (PMID 28656962, 2017). "Reintroduction of wild-type FLCN, but not tumour-associated FLCN mutants, suppresses EGFR signalling in a Rab7A-dependent manner." (PMID 28656962, 2017). "Similarly, the downregulation of RAB5C, RAB7A, and DNM2, involved in endocytosis and vesicular trafficking, suggests interference with receptor signaling, nutrient uptake, and protein degradation, essential for tumor growth." (PMID 40429900, 2025). "Normal and tumour tissues from such patients were analysed by qRT-PCR for the following 12 genes; six from RNA-seq: CLDN1, MAGEB2, CD24, CEACAM6, IL1B and ISG15 and six from RNA-seq and proteomics cross-linking: AKR1C3, TNFAIP2, RAB7A, LGALS3BP, PSCA and SSRP1." (PMID 36428603, 2022). "However, RAB7A silencing decreased exosomal release in MCF7 cells but did not have any effect on exosomal secretion in HeLa B6H4 tumor cells." (PMID 30626032, 2019). "Furthermore, we provided biochemical evidence indicating that FLCN WT protein, but not a tumour-associated missense FLCN mutant, increased the GTP hydrolytic activity of Rab7A." (PMID 28656962, 2017). "The decrease of RAB7A expression observed in absence of myoferlin could therefore reflect another mechanism that could explain the observed anti-tumor effect." (PMID 27845903, 2016). "The expression level of endogenous Rab7A was the same across all of the different growth conditions (regular media, serum-free media or media without growth factors and amino acids) and was not affected by expression of FLCN WT or the tumour-associated mutants." (PMID 28656962, 2017).
infection (18 papers, 2011 to 2026). The state of being infected such as from the introduction of a foreign agent such as serum, vaccine, antigenic substance or organism. "Host gene variants involved in trafficking (FYCO1 and RAB7A) and immune signaling (FOXA2, SFTPD, STAT3, and TET2) were associated with differential infection profiles." (PMID 41683583, 2026). "RAB7A expression peaked at 48 h post-infection (~6-fold increase vs. control, p < 0.001) and remained ~2.5-fold elevated at 72 h (p < 0.01)." (PMID 41012666, 2025). "The data reflects how important RAB7A is for infection of phylogenetically different viruses and the degree of likely convergent evolution that can occur in targeting the same host interface region." (PMID 40661470, 2025). "Using confocal microscopy, we confirmed the proteomic findings that Rab7a accumulates on FCV after 60 min of infection." (PMID 39458259, 2024). "The identification of 13 Rab family small GTPases and 4 vacuolar ATPase subunits and the characterization of Rab7a and VatA by confocal microscopy indicate their role in host–pathogen interaction after infection." (PMID 39458259, 2024). "RAB7A was a key regulator in endolysosomal trafficking, playing important roles in neurotrophin transport, lipid metabolism, microbial pathogen infection, and survival." (PMID 30918899, 2019). "At the same time, RAB7A also plays an important role in the infection and survival of microbial pathogens." (PMID 30918899, 2019). "Cells expressing C/A or D/N Rab7a showed a statistically significant (p < 0.05) average decrease in infection of 41.56 and 30.42%, respectively, when compared to cells expressing the WT protein." (PMID 25869659, 2015). "Follow‐up perturbation analysis showed that infection required Rab7a and PIKfyve, confirming that VACV is a late‐penetrating virus dependent on macropinosome maturation." (PMID 25869659, 2015). "Collectively, the localization, RNAi screening and infection data indicate that recruitment of functional Rab7a to MV‐containing macropinosomes is critical for VACV infection." (PMID 25869659, 2015). "Twenty-four hours after infection, the impact of Rab7A depletion on the production of infectious HIV-1 was assessed." (PMID 22072966, 2011). "Similarly, RAB7A, a small GTPase governing late endosome trafficking and maturation, was upregulated during infection." (PMID 41012666, 2025). "By 72 h, as infection became established, Rab7A levels tapered but stayed above control levels." (PMID 41012666, 2025). "To assess the effect of the Rab family on RSV replication, we depleted Rab1a, Rab2a, Rab4a, Rab5a, Rab6a, Rab7a, Rab8a, Rab9a, and Rab11a by treating A549 cells with specific siRNAs (or control siRNA) for 24 h, followed by infection with purified RSV A2 and incubation for another 36 h." (PMID 33504607, 2021). "Indeed, four days post-infection only a few infected cells were observed in Rab7A-depleted cultures and the level of CAp24 in the cell supernatants was 30-fold lower than the control." (PMID 22072966, 2011). "Through in vivo and in vitro experiments, we confirmed that SESN2 could inhibit this “infection” through the reduction of exosome release by promoting autophagic degradation; Rab-7a-mediated autophagosome and lysosome fusion and TFEB-mediated lysosomal function repair may play roles in this process." (PMID 40612680, 2025). "Of three studies employing Rab7a DN mutants, only one showed a moderate increase in HPV infection and found that overexpressing wild-type Rab7a slightly enhanced infection." (PMID 31475144, 2019). "Whereas depletion of either factor impairs Brucella intracellular replication, only RAB7A knockdown showed a marked effect on pathogen entry, whereas VPS35 appears to be required only at a later stage of the infection." (PMID 31243080, 2019). "By one hour post-infection, CD36 was widely distributed on the cell membrane and co-localized with mCherry-Rab7a at numerous cytoplasmic vesicles and at the PV membrane." (PMID 27280707, 2016).
infection (continued). "Representative images of amoebae expressing Rab7a-GFP show that F. novicida does not colocalize with GFP-Rab7a in D. discoideum 15 min after infection." (PMID 39458259, 2024). "Unlike Tfn, fluid-phase uptake (70 kDa Dextran), lysosomal (LysoTracker) and late endosomal (Rab7a) markers were not recruited at EPEC-wt infection sites." (PMID 31242273, 2019). "Furthermore, JUNV infection induced the colocalisation of p62, ATG16, RAB5, RAB7A and LAMP1 with the autophagosomal LC3 protein." (PMID 31216340, 2019). "The accumulation of virus clusters at the cell surface has been previously observed following infection of BST2-expressing cells with Vpu-defective HIV-1, suggesting that the effect of Rab7A knockdown on HIV release could be related to BST2 expression." (PMID 22072966, 2011). "Furthermore, the sensitivity of HIV-1 fusion and infection to Rab5A knockdown but not to Rab7A knockdown suggests that HIV-1 may tend to fuse in early endosomes of CEM cells." (PMID 30691001, 2019). "Our results showing that JUNV infection induces the colocalisation of RAB5, RAB7A or LAMP1 and LC3, indicate that phagophore or autophagosome fusion with early and late endosomes is not being blocked by JUNV infection." (PMID 31216340, 2019). "On the other hand, infection with MHV-S2′FCS was significantly diminished by downregulation of the early endosomal proteins RAB5B and RAB5C, but not of the late endosomal proteins RAB7A and RAB7B or the HOPS complex components VPS11 and VPS41 (blue bars)." (PMID 25375324, 2014).
peripheral neuropathy (6 papers, 2013 to 2024). A disorder affecting the peripheral nervous system. "CMT2B is a rare hereditary peripheral neuropathy resulting from five missense mutations in the RAB7A (ras-related protein Rab-7a) gene, responsible for encoding a small GTPase within the RAB (ras-related in the brain) family." (PMID 38607048, 2024). "From the perspective of neurological diseases, RAB7a missense mutations underlie the inherited peripheral neuropathy, Charcot-Marie-Tooth type 2B (CMT2B), while TBK1 mutations are associated with ALS." (PMID 30857122, 2019). "The fact that RAB7A could regulate peripherin assembly and thus peripherin functions reveals a new mechanism that may potentially explain the peripheral neuropathy caused by RAB7A mutations." (PMID 23179371, 2013). "The presence of RAB7A effector protein expressed only in certain kinds of neurons and, in particular, in neurons of the peripheral nervous system might explain why mutations in a ubiquitous protein such as RAB7A cause a specific peripheral neuropathy." (PMID 23179371, 2013). "Although these biochemical and functional data obtained with CMT-causing RAB7A mutants start to unravel the molecular mechanisms underlying CMT2B, it is not yet clear why expression of these mutant proteins specifically lead to a peripheral neuropathy." (PMID 23179371, 2013).
bacterial infections (1 paper, 2025). "Ras-related protein Rab-7a (RAB7A) plays an important role in endolysosomal trafficking and has been shown to be involved in viral and bacterial infections across many pathogens." (PMID 40661470, 2025).
RAB7A also shares sentences with these, for which no sentence is quoted: glioma (3 papers); neurodegenerative disease (3); neurologic disease (3); Sensory neuropathy (3); hepatocellular carcinoma (2); liver cancer (2); cardiovascular diseases (1); COVID-19 (1); diffuse peritoneal malignant mesothelioma (1); Encephalopathy (1); genetic disorder (1); hematological cancer (1); Hyperkeratosis (1); Hyperreflexia (1); keratitis (1); lysosome disease (1); major depressive disorder (1); mild cognitive impairment (1); multiple myeloma (1); myopathies (1); neuroblastoma (1); neurotoxicity (1); Niemann-Pick disease (1); paraplegia (1); Salmonella Infections (1); Sensory axonal neuropathy (1); sensory impairment (1); Skin ulcer (1); small cell lung carcinoma (1); Spastic paraplegia (1).
A further 3 diseases each share a sentence with RAB7A in 1 paper.